SNORA70B (small nucleolar RNA, H/ACA box 70B)
Gene: Small nucleolar RNA gene on chromosome 2 (61,417,244 to 61,417,378, reverse strand). Ensembl gene ENSG00000206937.
Gene Ontology:
Biological process: RNA processing
Cellular component: nucleolus
Homologues: Orthologues: chimpanzee SNORA70 (99% identical). Paralogues in human: SNORA70H (94% identical), SNORA70G (91% identical), SNORA70J (91% identical), SNORA70 (90% identical), SNORA70I (90% identical), SNORA70C (90% identical), SNORA70F (88% identical), SNORA70 (87% identical), SNORA70E (86% identical), SNORA70D (85% identical), SNORA70 (84% identical), SNORA70 (81% identical), and 14 more.
Diseases named in the same sentence as SNORA70B in open-access papers:
SNORA70B is named in the same sentence as 2 diseases in open-access papers, as found by Europe PMC text mining. Sharing a sentence is not in itself a finding about the gene and the disease.
SNORA70B shares sentences with these, for which no sentence is quoted: dementia (1 paper); renal diseases (1).